ID1 (inhibitor of DNA binding 1)
Diseases named in the same sentence as ID1 in open-access papers (continued):
Sharing a sentence is not in itself a finding about the gene and the disease.
cancer (continued). "Consistent with dedifferentiation of adult tissues being intricately connected to oncogenesis, the evidence for an important role of Id1 in cancer development and progression seems to be growing." (PMID 24970809, 2014). "Overexpression of Id1 and Id3 has been correlated with an unfavorable prognosis in a variety of cancer types and a recent study suggested Id1 and Id3 co-expression was related to poor clinical outcome in stage III-N2 non-small cell lung cancer (NSCLC)." (PMID 25061504, 2014). "Id1 has been reported to regulate invasion, proliferation, survival, and the metastatic spread of cancer cells." (PMID 23593444, 2013). "Cancer cells with low expression of Id1 (Id1 low) were highly proliferative with little ability to self-renewal." (PMID 24160469, 2013). "Since ID1 promotes cell proliferation and invasion, it has been proposed as an attractive target for cancer therapy." (PMID 24137437, 2013). "The correlation between Id1 and Id3 and its functional implications have been studied in other cancers." (PMID 23311395, 2013). "Self-renewal and chemotherapy resistance in cancer-initiating cells is mediate through the expression of inhibitor of differentiation/DNA binding proteins Id1 and Id3." (PMID 24160469, 2013). "ID1, an inhibitor of basic helix-loop-helix transcription factors, has been shown to be a key regulator of a number of steps in cancer progression." (PMID 24137437, 2013). "Id1 has been shown to inhibit differentiation, to stimulate proliferation and to be expressed by embryonic stem cells, adult stem cells and cancer stem cells, thus making it a logical candidate to investigate." (PMID 23691228, 2013). "Studies have shown that Id1 mediates self-renewal of “cancer stem cells” and resistance to chemotherapy." (PMID 24160469, 2013). "Our results demonstrating a different role of Id1 and Id2 in ACCM cells suggest that SGCs differ from other types of cancer in which Id1 and Id2 appear to play a more equivalent role." (PMID 23517130, 2013). "In fact, elevated Id1 and Id3 protein levels have been found in vitro and by immunohistochemistry in samples of many different human carcinoma types supporting the role of both genes in carcinogenesis." (PMID 23311395, 2013). "Cytoplasmic Id1 staining had been reported in a number of studies including prostate, breast, and gastric cancers." (PMID 23342268, 2012). "In Id1 positive prostate (grades I through III) cancer specimens, Id1 staining was nuclear, but cytoplasmic staining was also observed (grade III, 200× and 400×, respectively)." (PMID 23342268, 2012). "Taken together, ID1-driven inhibition of differentiation is a plausible mechanism for the impaired acinar morphogenesis accompanied by cancer-like expression of marker genes at hypoxia." (PMID 23029547, 2012). "In spite of strong sequence similarity and assumed functional redundancy, the function of Id3 in promoting a cancer phenotype now appears to be distinct from Id1." (PMID 23342268, 2012). "It has been shown that ID1 is de-regulated in multiple cancers and up-regulation of ID1 is correlated with high-grades and poor prognosis in human cancers." (PMID 22355333, 2012). "Id1 is often found to be overexpressed in cancer cells and contributes to malignant properties of cancer cells including cell proliferation, invasion and angiogenesis." (PMID 21701587, 2011). "In the present study, we provide evidence that SKI-606 and, to a lesser extent, Iressa inhibit cell invasion and migration of HeLa and SiHa cancer cells; this is accompanied by a downexpression of P-cadherin, fascin, Id-1, IGF-R1 and EGF-R." (PMID 20862378, 2010). "Delineation of the molecular mechanisms of Id-1 in prostate carcinogenesis and cancer progression has recently begun." (PMID 20010941, 2010). "Id1 has multiple oncogenic functions imparting resistance to TNFα and anti-cancer drug-induced apoptosis." (PMID 20565867, 2010).
cancer (continued). "Within these transcription factors, ID1 is known for its function in tumorigenesis and also a possible therapeutic target for cancer treatment." (PMID 20707922, 2010). "Contrary to the oncogenic role assigned by the literature, our analysis in Oncomine indicates that SLC7A5 and ID1 are negatively correlated with cancer progression." (PMID 20500816, 2010). "Although ID-1 has been shown to interact with various cell cycle regulators, ID-1 seems to be an essential factor in the promotion of G1/S cell cycle transition in certain cancers by inactivating of p16 and increasing of CDK4 activity/RB." (PMID 19002177, 2008). "ID1 basal levels are elevated in a variety of cancers, and ID1 is induced during malignant transformation of rat liver cells by arsenic." (PMID 16966095, 2006). "Importantly, the upregulated expression of CREB3L1 and BCAS1 and downregulated expression of ID1 and ID3 appeared least impacted by the co-existing 2nd (cancer) pathway variants based on visualisation of the heat maps." (PMID 40348815, 2025). "Furthermore, administration of AGX‐51 reduced the availability of VEGF, the leading angiogenic protein essential for neovascularisation and vascular permeability, documented to promote VM by cancer cells and a known regulatory target of ID1." (PMID 40116596, 2025). "Interestingly, TBX3 has been shown to promote cancer cell migration via activation of inhibitor of DNA binding 1 (ID1), a negative regulator of CDH1." (PMID 40001874, 2025). "Both ID1 and RSAD2 have been implicated in regulating glycolytic pathways in cancer." (PMID 39334961, 2024). "ID-1 has been shown to regulate multiple metabolic pathways in other cancer types." (PMID 39455562, 2024). "BMP9 and ID1 play important roles in the occurrence, development, and invasion of malignant tumors." (PMID 39619441, 2024). "Most of the previous studies reported a high expression of ID1 in many kinds of cancers." (PMID 37964494, 2024). "On the basis of these observations, we thus speculate that BVZ could have an effect on cancer cells, and that ID1-overexpressing cells may have reduced dependence on VEGF/VEGFR2 signaling, potentially contributing to an attenuation of the efficacy of BVZ." (PMID 38658527, 2024). "While ID1 was the most significantly upregulated in SMAD4-expressing tumors, it is a well-known target of BMP4 and has been implicated in the promotion of metastasis in different cancer types." (PMID 38689334, 2024). "Notably, the components in the newly identified AKT/mTOR/STAT3/ID1 axis play pivotal roles in cancer metastasis." (PMID 38183094, 2024). "The possibility of pharmacologically targeting Id1 with trametinib in human cancers could offer a therapeutic alternative for those KRAS-mutant LUAD patients who poorly respond to ICIs or develop early acquired resistance." (PMID 38643157, 2024). "Whilethe modulation mechanism remains unclear, there is evidence that melatonincould modulate the DJ-1/KLF17/ID-1 signaling pathway to prevent theexcessive mitotic activities, as shown with the occurrence of cancer." (PMID 37676068, 2023). "Y15 was further used to verify whether ID1 expressing TAMs maintain cancer stemness traits through activation of FAK signaling." (PMID 37996458, 2023). "Id1 is a stem cell‐like gene and is overexpressed in several types of cancers." (PMID 37085918, 2023). "The finding of a conserved up-regulation of ID1 may provide molecular support to the involvement of PFAS molecules in cancer pathogenesis." (PMID 37505532, 2023). "From the therapeutic angle, both cancer stem cells and protumorigenic TAMs are addicted to ID1, suggesting that ID1 may be a promising anticancer target." (PMID 37996458, 2023). "Additionally, we have furnished compelling evidence that Orai3 significantly advances the progression of OSCC by amplifying cancer stemness through the elevation of ID1 expression." (PMID 37759448, 2023).
cancer (continued). "More surprisingly, ID1 was the top one transcriptional factor gene and was dramatically upregulated and specific in cancer cells, suggesting that ID1 might be critical for the PDAC development in human." (PMID 35941362, 2022). "ID1 and ID2 are characterised predominantly by insertions and deletions of single T bases at T mononucleotide repeats which are associated with strand slippage during DNA replication and are seen in most human cancers and normal tissues." (PMID 35803914, 2022). "Considering the ubiquitous nature of ZNF148 expression, the MYC, ZNF148, ID1/3 regulatory axis may be present in a broad array of cancers driven by MYC and ID proteins." (PMID 36207293, 2022). "Collectively, miR-524-5p exerted the anti-cancer role via inhibiting ID1 expression in PTC cells." (PMID 35635748, 2022). "CBD has previously been shown to decrease expression of ID1 in various cancers." (PMID 35954477, 2022). "In addition to the Wnt, Shh, and TGF-β signaling pathways, research in other cancers has linked ID-1 to K-ras signaling, PI3K/Akt signaling, and STAT3 signaling, illustrating the centrality of ID-1 across multiple signaling pathways." (PMID 35954407, 2022). "The downregulation of ID1 gene expression using antisense oligonucleotides or compound inhibitors alleviates cell proliferation, promotes cell differentiation, and suppresses invasiveness in cancer." (PMID 35806401, 2022). "Taken together, NEAT1 functioned as a cancer promoter by regulating miR-524-5p/ID1 axis in PTC." (PMID 35635748, 2022). "Surprisingly, Id1 transcription levels were increased with the principal curve of the differentiation potential, further suggesting that Id1 was critical for the progression of the cancer." (PMID 35941362, 2022). "Thus, other signals or cofactors from the cancer stem cell niche that modify or affect transactivation of NF-κB or ID1 are needed to transform keratinocytes." (PMID 33442406, 2021). "Our previous study also found that LEF1 of the Wnt signaling pathway could directly bind to the promoter of ID1 and promoted cancer stem‐like properties in ESCC." (PMID 33463006, 2021). "Finally, we examined the expression of genes that are known to be associated with migration and metastasis of cancer cells, and we observed a significant reduction in E-cadherin (CDH1), an inhibitor of differentiation 1 (ID1) and TWIST2." (PMID 34440702, 2021). "First, we selected the down-regulated genes at PNX0010 under PARG overexpression that are related to cancer development: ID1, ID2, ID3, and SERPINE1 and performed qPCR analysis for 786-O, 769-P, SK-RC-45, and SK-RC-26b cell lines treated with the 10 uM PARP-1 inhibitor rucaparib for 24 h." (PMID 34638458, 2021). "In cancer cells, ID1 transcription is upregulated by TGFβ/Smad3 signaling." (PMID 33990575, 2021). "Since ID1 is a well-established oncoprotein that promotes cancer cell survival and proliferation, we hypothesize that the increase of ID1 may confer adaptive resistance to HIF1α-targeted inhibition." (PMID 34820369, 2021). "However, genes associated with cell differentiation (EPCAM, CK8, CK18, and FOXA2), EMT (SNAI1, FOSL1, and ID1), and cancer stem cells (CD44, CD133, ETV1, MALAT1, NEAT1, and NESTIN) displayed a more varied response compared to 2D cells." (PMID 33356003, 2021). "Additionally, we found that E6/E7 of HPV type 16 provoke cell-invasive and metastatic abilities in vitro and in vivo, accompanied by Id-1 overexpression, which regulates cell invasion and metastasis of cancer cells." (PMID 32325943, 2020). "Based on the outcome that lowly expressed ID1 might promote cancer cell metastasis and thereby influence patient's survival time, we supposed that ID1 probably affect immune system." (PMID 33178820, 2020). "While evidence also suggests that Id1 is a key factor in promoting cancer metastasis to lungs 68, the discrepancy of microenvironment in different sites may be the cause." (PMID 32410828, 2020).
cancer (continued). "Thus, we have uncovered a mechanism in which ID1 confers cancer cell chemoresistance largely through the STAT3/ATF6-induced autophagy." (PMID 32080166, 2020). "As such, ID1 may serve as novel therapeutic target for skewing myeloid cells towards a less immunosuppressive and more immunogenic phenotype in cancer patients." (PMID 31953577, 2020). "Furthermore, Id1 is known to enhance cell proliferation, DNA synthesis, migration and invasion of various cancer cells." (PMID 31100813, 2019). "Of note, the lower inhibitory efficiency of dark tea extract for cell growth in HPDE cells than in cancer cells is observed in our study, which would be related to the limited ID1 expression levels in HPDE cells, as ID1 levels was found to be positively related to cancer cells growth." (PMID 31777585, 2019). "Many studies indicate that ID1 is an oncogene and is critical in promoting cancer progression." (PMID 31296250, 2019). "The presence of VEGF antibody could also abolish the enhanced migration of VEGFR1+ bone marrow cells attracted by the co-culture of fibroblasts with Id1-expressing cancer cells." (PMID 28186102, 2017). "One gene involved in free radical scavenging, SOD3, was downregulated, whereas the genes associated with cell cycle or cancer, including GADD45B, ID1, KLF10, CSRNP1, and TM4SF1, were upregulated in F. nucleatum-infected GF(P22) cells when compared to F. nucleatum-infected GF(P4) cells." (PMID 29190775, 2017). "Based on these results, we suggest that the downstream signaling pathways of Id-1-mediated cell proliferation may differ between cancer types." (PMID 29233161, 2017). "Increasing evidence indicates that ID1 is involved in many malignant biological phenotypes such as cell proliferation, immortalization, invasion, and metastasis in different types of human cancer." (PMID 29169374, 2017). "Additionally, genes normally upregulated in several types of cancer cells (Sema3c, Id1, Cxcl1, Ctgf) appear downregulated by Pdrg1 silencing." (PMID 27548429, 2016). "Id1 has also been shown to promote survival of cancer cells by activating NF-kappa B." (PMID 27048361, 2016). "KLF17 low expression increases cancer metastatic viability; its mechanism is that low KLF17 mediates epithelial-mesenchymal transition (EMT) through regulating EMT-related genes expression; the reduced-KLF17 also increases cancer metastasis though upregulating inhibitor of DNA binding 1 (ID1)." (PMID 26662959, 2016). "Because the canonical Wnt signaling pathway plays an essential role in regulating self-renewal of both normal and cancer stem cells, we explored whether Id1 enhanced normal and malignant mammary stem cell activities through this pathway." (PMID 25938540, 2015). "Id1 and/or Id3 may be better targets in other cancer types for inducing the attenuated, immunogenic effect observed following Id2 knock down in Neuro2a cells." (PMID 26079374, 2015). "Id1 also modulated both breast normal and cancer stem cells via the Wnt/TCF/c-Myc pathway." (PMID 25938540, 2015). "The function of FSCN1 and ID1 in promoting normal angiogenesis and cancer metastasis is well known." (PMID 26167915, 2015). "Since the Inhibitors of DNA binding/differentiation (Id) family members are direct mediators of the BMP signaling, and they are involved in invasion, proliferation and metastasis of cancer cells, we measured the gene expression of Id1, Id2 and Id3 in A549 by qPCR." (PMID 24603907, 2014). "Abnormal expression of ATF3 may mediate multiple aspects of cancer biology by repressing the transcription of certain downstream molecules including Cyclin D1, Id1 and IRS2." (PMID 25149542, 2014). "Therefore, Id1 and NF-κB are important oncogenic proteins in keeping cells in a state of naiveness and proliferation and thought to contribute to the generation of cancer initiating cells." (PMID 24572994, 2014).
cancer (continued). "Over-expression of ID1 has been correlated with a variety of human cancers; our earlier studies had shown that reported ID1 is induced by nicotine or EGF stimulation of non-small cell lung cancer (NSCLC) cells and its down regulation abrogates cell proliferation, invasion and migration." (PMID 25028095, 2014). "In addition to cell survival, we now learn that Id1 also makes cancer cells naïve by increasing the expression of CD133." (PMID 24572994, 2014). "How these ID proteins maintain the cancer stem-cell phenotype is not known, but the response of GCSCs to TGF-β receptor inhibitors by reducing ID1, ID3 proteins and cell surface CD44 is very important as such markers appear to be functionally linked to the cancer-initiating phenotype of GCSCs." (PMID 23998913, 2013). "Several studies have shown that Id1 inhibits apoptotic cell death of cancer cells." (PMID 23593444, 2013). "In addition, Egfr (epidermal growth factor receptor), Gadd45A (growth arrest and DNA-damage-inducible protein) and Id1 (inhibitor of differentiation) are well known to function in cancer pathways." (PMID 23922661, 2013). "The evidences here presented suggest that additional genes such as TCF3 and ID1 could also mediate EMT in basal-like carcinomas." (PMID 23555842, 2013). "Among those, we identified the known BMP-2 target genes Id1, Id3, Dlx2 and Hey1, and genes that could be functionally annotated to Wnt signaling, pathways in cancer or cytokine-cytokine receptor interaction and that have critical roles in osteogenesis." (PMID 21998639, 2011). "Over-expression of Id1 has been widely observed in human cancers where it may play a critical role in tumourigenesis and cancer progression." (PMID 20565867, 2010). "Over-expression of Id1 has been observed in a variety of cancers where it may contribute to a variety of cellular functions that include cell proliferation, resistance to apoptosis, angiogenesis, invasion and inhibition of terminal cell differentiation." (PMID 20565867, 2010). "Our findings here were very suggestive that endogenous ID1 expression might also influence centrosomal homeostasis in various cancer cell lines." (PMID 20070914, 2010). "The importance of Id-1 in the metastatic progression of various types of cancer has been shown." (PMID 20010941, 2010). "Functional studies have demonstrated that Id1 is able to promote cell proliferation, delay senescence in primary human cells, and promote cell migration and the metastatic phenotype of cancers." (PMID 20414347, 2010). "Thus, ID1-expressing cells are particularly numerous in the bone marrow in which there are relatively few cancer cells." (PMID 19491902, 2009). "In addition, our findings suggest that the ID1 expression originates from not only the cancer cells but also the host side progenitor cells with the cancer-bearing condition." (PMID 19491902, 2009). "The tumor suppressor role of Id4 appears to be unique as compared to other members of the Id gene family (Id1, Id2 and Id3) that may act as oncogenes or co-operating oncogenes in many cancers." (PMID 19500415, 2009). "Inhibitor of DNA-binding-1 staining was diffusely located in the cancer cells." (PMID 19002177, 2008). "The results of this study support the idea that not only EGFR and VEGF but also Id-1 could be new targets in cancer treatment." (PMID 19014499, 2008). "Most of the cancer specimens had positive staining for Id-1, EGFR and VEGF." (PMID 19014499, 2008). "Id-1 has been shown to promote metastasis in several different types of cancer." (PMID 18000500, 2007). "In addition, Id-1 seems to be an essential factor in the promotion of G1/S cell cycle transition in certain cancers by inactivating of p16 and increasing of CDK4 activity/RB." (PMID 15026801, 2004). "It appears that Id-1 protein may be an important new target molecule for antiangiogenic drug design in cancer treatment." (PMID 15026801, 2004).